LAG3 (lymphocyte activating 3)
Diseases named in the same sentence as LAG3 in open-access papers (continued):
Sharing a sentence is not in itself a finding about the gene and the disease.
cancer (continued). "Maruhashiet al have demonstrated that stable peptide-MHC II, rather than fibrinogen-like protein (FGL1), serves as the functional ligand for LAG3-mediated T cell suppression in both autoimmunity and anti-cancer immunity." (PMID 40420606, 2025). "Because of the limited efficacy of blocking TIGIT alone, these approaches to targeting TIGIT should be flexibly combined with other immunotherapies, such as anti-PD-1/LAG-3 or cancer vaccines." (PMID 40890162, 2025). "While anti-CTLA4 and anti-PD1 are standard treatments for many solid tumors, TIGIT and LAG3 have emerged as promising new targets for cancer immunotherapy." (PMID 40067762, 2025). "Immunohistochemistry analysis revealed that LAG-3 is expressed in various cancer tissues, with 90% of NSCLC and 52% of SCLC samples having detectable positive LAG-3 expression." (PMID 40510353, 2025). "Immune checkpoint molecules, including CTLA4, PD1, and LAG3, serve crucial roles in immune homeostasis by modulating immune responses and preventing excessive tissue damage, which is often exploited by cancers and pathogens to escape immune control." (PMID 40459260, 2025). "The expression of LAG‐3 has been found out in in several cancers, including pancreatic ductal adenocarcinoma." (PMID 40415479, 2025). "T-cell immunoreceptor with Ig and ITIM domains (TIGIT) and lymphocyte-activation gene 3 (LAG-3) are newly identified immune checkpoint molecules that play critical roles in immune suppression in various cancers." (PMID 40861435, 2025). "Peptide inhibitors of LAG-3 are a rapidly developing class of therapeutic molecules that show promising potential in cancer immunotherapy by selectively blocking the interaction of LAG-3 with its ligands." (PMID 40574024, 2025). "These compounds not only validate LAG-3 as a druggable target beyond mAbs but also pave the way for future oral immunotherapies with the potential to enhance immune responses in cancer and chronic infections." (PMID 40574024, 2025). "T cell activation and function are modulated by cancer cells via the expression of ligands for co-inhibitory receptors, like programmed death 1 (PD-1) or lymphocyte activation gene 3 (LAG-3)." (PMID 40282480, 2025). "SELENOP and CD244 were highly expressed in the adjacent cancer tissues, while PKMYT1 and LAG3 were highly expressed in the cancer tissues." (PMID 40821907, 2025). "Despite the therapeutic potential, the complexity of LAG-3 as a prognostic marker in cancer still requires further exploration." (PMID 39660130, 2024). "The results of IHC revealed that CCL14 expression in cancer cells was related to immune checkpoints LAG3 and PD-L1." (PMID 38887558, 2024). "This review discusses the function of LAG-3 in regulating immune responses, the effect of LAG-3 interaction with ligands, the significance of LAG-3 as a prognostic biomarker in cancer patients and the potential therapeutic strategies targeting LAG-3." (PMID 39660130, 2024). "Studies evaluating the predictive potential of LAG3 in cancer patients are an active area of research." (PMID 38277212, 2024). "In a nutshell, LAG-3 has emerged as a viable option for cancer immunotherapy, but more study of these strategies is critical, particularly in the older population, where LAG-3 expression is significantly higher than in younger people." (PMID 38590525, 2024). "Meanwhile, anti-LAG-3 therapy has also been explored for cancer immunotherapy in both preclinical studies and clinical trials." (PMID 38724599, 2024). "Similar to PD-1, constitutive LAG3 expression is associated with exhausted T cells (CD4 and CD8 T cells) in cancer and chronic viral invasions." (PMID 39211038, 2024). "In preclinical models of cancer and chronic viral infection, it has been observed that the blockage of LAG-3 reverses T-cell exhaustion." (PMID 39422598, 2024). "Antibodies targeting PD-1, CTLA-4 and more recently LAG-3 have improved cancer outcomes in many settings." (PMID 39273028, 2024).
cancer (continued). "According to TCGA KIRC RNA-seq data, LAG3 was overexpressed in both paired and unpaired cancer tissues as compared to healthy controls." (PMID 38277212, 2024). "This research demonstrated that combination therapy with anti-LAG-3 and anti-PD-1 slowed cancer progression by restoring and enhancing effector T cell populations in tumors and lymph nodes." (PMID 39660130, 2024). "Here, we carried out the most extensive and detailed study up-to-date on PD-1/LAG-3 co-expression as a signature of potent immune dysfunctionality in human cancers and T-cells." (PMID 39030301, 2024). "CTLA-4, PD-1, and lymphocyte activation gene 3 (LAG-3) immune checkpoints can be classified as immunotherapeutic targets that impede cancer growth." (PMID 38533510, 2024). "In conclusion, although LAG-3 inhibitors hold tremendous potential in cancer immunotherapy, future research faces numerous challenges." (PMID 39743998, 2024). "Classical ICIs, such as programmed cell death protein-1 (PD-1), PD-L1, cytotoxic T-lymphocyte-associated antigen 4 (CTLA-4), and lymphocyte activation gene-3 (LAG-3) inhibitors, have been approved for the treatment of various cancers." (PMID 38627681, 2024). "In this comprehensive review, we delve into the biological mechanisms underlying the most frequently targeted ICPs in cancer therapy, including CTLA-4, PD-1, PDL-1, and LAG3." (PMID 39359534, 2024). "In spite of the potential application value of LAG-3 in cancer immunotherapy, its functional mechanisms remains obscure." (PMID 38177102, 2024). "This response was seen to be better than just targeting one or the other, thus showing the likelihood of the similarity and co-expressions of PD-1 and LAG-3 in cancer cells." (PMID 39796650, 2024). "We then address the development and mechanisms of action of anti-LAG3 mAbs in clinical trials for cancer immunotherapy." (PMID 38556085, 2024). "Immune checkpoint blockade (ICB) therapies targeting PD1, CTLA4 and LAG3 on CD8+ TIL has proven to be a particularly effective modality of cancer treatment." (PMID 39516648, 2024). "Overall, the present study determined ADAM10 expression by AD, CD and m62A, and in AD or CD/ADAM10/LAG3 signaling in cancers, and suggested a potential method for immunotherapy of cancers by targeting ADAM10 using the small molecules AD, CD and m62A." (PMID 39211038, 2024). "Individual interactome networks for activated PD-1 and LAG-3 pathways or their combination were modelled (Fig. EV2D), and the correlation of the identified molecules with PDCD1/LAG3 expression was validated on human cancers with TIMER2.0 (Fig. EV2E)." (PMID 39030301, 2024). "Immune checkpoint receptors, including CTLA-4, PD-1, PD-L1, and LAG-3 (Lymphocyte activation gene 3), are inhibitory molecules present on the surface of immune cells, cancer cells and other supporting cells in the TME." (PMID 38279265, 2024). "The findings revealed that 22 genes, including key immune checkpoint molecules such as PDCD1, TIGIT, and LAG-3, were significantly upregulated in hot tumors across all five cancer types." (PMID 39911580, 2024). "Perform a bibliometric analysis on the role of LAG-3 in the domain of cancer, elucidate the prevailing areas of research, and visually depict the evolutionary trajectory and prospective directions of LAG-3 research over the past twenty-three decades." (PMID 38390331, 2024). "In Turnis’ study, over 75% of mice with MC38 cancer or Sa1N fibrosarcoma were effectively treated with a combination of anti-PD-1 and anti-LAG-3 antibodies, resulting in complete clearance of tumors and prolonged survival." (PMID 38581716, 2024). "Relatlimab, an anti-LAG-3 monoclonal antibody, has shown encouraging results, especially when combined with nivolumab, to enhance treatment in patients with advanced cancer." (PMID 39660130, 2024).
cancer (continued). "By inhibiting LAG-3, Incagn-2385 aims to enhance the body’s immune system in recognizing and attacking cancer cells, potentially leading to improved therapeutic outcomes for patients with advanced malignancies." (PMID 39743998, 2024). "This process, which ends in the upregulation of PD-1 and LAG-3, is clearly regulated by YY1, and causes T cell exhaustion and the persistence of various cancers." (PMID 39796650, 2024). "But are the therapeutic effects of targeting LAG3 through direct cancer killing or by indirect immune modulating?" (PMID 38539487, 2024). "Lymphocyte-activation gene 3 (LAG-3) has emerged as a key immune checkpoint regulating immune responses in the context of cancer." (PMID 39660130, 2024). "In this review we focus on the biology of LAG‐3 and aim to summarize what is known regarding expression, ligands, and mode of action of this emerging target in cancer immunotherapy." (PMID 39560030, 2024). "This has directed considerable attention to LAG3, the third immune checkpoint receptor to be exploited for cancer immunotherapy." (PMID 38556085, 2024). "This study demonstrates the potential efficacy of a synergistic approach involving anti-LAG-3/anti-PD-1 immunotherapy in reducing cancer progression." (PMID 38390331, 2024). "We then direct our attention to the development and mechanisms of action of antagonist mAbs targeting LAG3 for cancer immunotherapy, including new therapeutic approaches." (PMID 38556085, 2024). "This review discusses the function of LAG-3 in immune suppression, its interactions with ligands, and its potential as a prognostic biomarker for cancers." (PMID 39660130, 2024). "Ultimately, the use of PD-1 and LAG-3 blockers has notably improved response and survival rates for numerous types of cancer." (PMID 38581716, 2024). "Many studies have demonstrated that dysfunctional CD8 T cells in cancer are characterised by high expression levels of inhibitory receptors, including PD-1, TIM-3, LAG-3, and TIGIT, which are positively associated with T cell exhaustion." (PMID 39676870, 2024). "The emergence of immune checkpoint therapies, especially those targeting PD-1 and CTLA-4, has revolutionized cancer treatment, and LAG-3 is expected to become an important therapeutic target in oncology." (PMID 39743998, 2024). "The varied mechanisms by which LAG-3 exerts a negative regulatory role in the immune system in addition to studies showing synergy with PD-1 make it an attractive target for cancer immunotherapy." (PMID 39346924, 2024). "Gal-3 is expressed in a variety of cancer cells and activated T cells, and it can interact with LAG-3 to inhibit cytotoxicity of CD8 + T lymphocytes." (PMID 38177102, 2024). "On the other hand, some studies have also reported that LAG-3 can be a biomarker for poor prognostic outcomes in some cancers." (PMID 39660130, 2024). "Further investigations are warranted to elucidate the risk of HZ in patients with different cancer types and those receiving treatment with other types of ICIs such as anti-CTLA-4, anti-LAG-3, and anti-TIM-3 inhibitors." (PMID 38672581, 2024). "The examination of the role of LAG-3 in cancer and its potential for use in clinical settings is a discernible trend, as seen by keyword analysis." (PMID 38390331, 2024). "Lymphocyte activation gene 3 (LAG 3) is another critical immune checkpoint, and a member of the immunoglobulin superfamily, which has been linked to cancer, autoimmune diseases, and infections." (PMID 38418707, 2024). "CCL14 protein expression in cancer cells was positively related to LAG3 expression (r = 0.536, p < 0.001) and PD-L1 (r = 0.518, p < 0.001)." (PMID 38887558, 2024). "BMS-986016 is a therapy that targets LAG-3 and is currently under investigation in combination with nivolumab, which targets PD-1, to enhance the immune response against cancer cells." (PMID 38410760, 2024). "Given its role in immune tolerance for cancer cells, LAG-3 blockade is being explored as a therapeutic target." (PMID 38322418, 2024).
cancer (continued). "TIGIT, CTLA-4, PD-1, T cell immunoglobulin 3 (Tim3), and lymphocyte activation gene 3 (LAG3) are the most commonly targeted checkpoints for cancer immunotherapy." (PMID 39349422, 2024). "RCCs that are LAG-3 + and PD-L1 + are associated with higher TNM staging and higher Fuhrman nuclear grades, and PD-L1+/LAG-3 + RCCs demonstrate poorer cancer-specific survival (CSS)." (PMID 39014460, 2024). "Both CTLA-4 and LAG-3 are co-suppressor receptors of T cells, which are associated with T cell activation and CD8+T lymphocyte failure caused by malignant tumors." (PMID 39252941, 2024). "Recent studies have shown that GSK-3β upregulates the expression of inhibitory receptors LAG-3 and PD-1 in T cells, highlighting its potential as a therapeutic target in cancer immunotherapy." (PMID 39340067, 2024). "We also used ImmuCellAI to explore the correlation between YY1, CD274, and LAG-3 expression and immune infiltration in various cancers." (PMID 39796650, 2024). "This review provides in-depth insight into the biology of LAG-3 and explores its current and future roles in cancer treatment." (PMID 39425148, 2024). "This differentiation is associated with poor responses to immunotherapy in cancer patients and the upregulated expression of “exhaustion” cell markers such as PD-1, TIM-3, LAG-3, TIGIT, and CTLA-4." (PMID 38727261, 2024). "v) An immune pathway known as LAG-3 has been identified as a potential complement to the PD-1/PDL1 pathway in enhancing the immune response against cancer." (PMID 38410760, 2024). "Here we have first systematically analyzed extensive multiomic data to extract PD-1 and LAG-3 omic signatures in all TCGA cancers to compare with PD-1/LAG-3-associated signatures in T-cell lines with constitutive PD-1 and LAG-3 signaling." (PMID 39030301, 2024). "LAG-3 has been identified as an up-and-coming candidate for immunotherapy for cancer and is further substantiated by extensive studies conducted on models of animals." (PMID 38390331, 2024). "Numerous studies have elucidated that the increased expression of LAG-3 is able to improve the clinical outcome of cancer patients." (PMID 39660130, 2024). "It was reported that elevated fibrinogen-like protein 1 (FGL1), a major LAG-3 functional ligand independent from MHC-II, is associated with a poor prognosis and resistance to anti-PD-1/B7-H1 therapy in cancer patients." (PMID 38724599, 2024). "Currently, with the approval of relatlimab, a LAG-3 blocking antibody, a third player, has been used in the fight against cancer." (PMID 39425148, 2024). "In this review, we provide in-depth insight into the biology of LAG-3 and its current and future development in cancer treatment." (PMID 39425148, 2024). "In this review, we discuss the regulation of LAG-3 by YY1 as proof of principle for the potential use of targeting YY1 as an alternative therapeutic approach to preventing the immune evasion of cancer." (PMID 39796650, 2024). "Several studies have indicated that elevated LAG-3 expression in TILs is related to an unfavorable prognosis in various cancers." (PMID 38672108, 2024). "In cancer, LAG-3 is often upregulated in tumor-infiltrating lymphocytes and is associated with T cell exhaustion." (PMID 38254772, 2024). "PD-1 and LAG-3 jointly drive T-cell exhaustion, with a critical role in modulating TOX expression, highlighting the potential of targeting both PD-1 and LAG-3 for more effective cancer immunotherapy." (PMID 39684559, 2024). "In brief LAG-3 is able to enhance regulatory T-lymphocytes levels through IL-10, resulting in a significant increase of cancer cells immune escape; therefore LAG-3 it is considered a new target of great clinical interest in cancer immunotherapy." (PMID 38322766, 2024). "Like other inhibitory receptors, LAG3 contributes to T cell exhaustion in chronic diseases and cancer, making it a target for cancer immunotherapy." (PMID 39064019, 2024).
cancer (continued). "We anticipate that the combining anti-TIGIT and anti-LAG-3 dual target therapy will be a novel approach to cancer immunotherapy." (PMID 38724599, 2024). "Lymphocyte activation gene 3 (LAG-3) has recently emerged as a promising new target in cancer immunotherapy." (PMID 39743998, 2024). "- LAG-3 rises with advancing age in normal and cancer tissues. - The PD-1 and LAG-3 co-expression patterns hold significant mechanistic importance, leading to a synergistic reversal of T -cell exhaustion." (PMID 38590525, 2024). "LAG-3 is a pivotal checkpoint molecule that potentially exhibits synergistic interactions with PD-1 and PD-L1 during cancer immunotherapy." (PMID 38672108, 2024). "Considering the popularity of LAG3 as a potential biomarker in cancer studies, a robust LAG3 assay should be developed." (PMID 37311986, 2023). "Ongoing trials are studying the combination of LAG-3 antibodies with PD-1 inhibitors in multiple cancers and settings." (PMID 37484526, 2023). "Additional research is needed to better understand the role and importance of LAG-3 in NK cell cancer killing." (PMID 38090565, 2023). "We utilized the GEPIA2 database to assess the survival outcomes of LAG3 in various cancers types, focusing on OS and DFS." (PMID 38115039, 2023). "LAG-3, or lymphocyte activation gene 3, is a protein expressed on the surface of certain immune cells and cancer cells." (PMID 37895833, 2023). "Lymphocyte-activation gene 3 (LAG3) is a highly anticipated immune checkpoint in the context of cancer, exerting regulatory control over immune cell proliferation and function to reinforce the advancement of cancers." (PMID 38115039, 2023). "Many clinical applications to inhibit the LAG-3/ligand binding have been developed for cancer treatment." (PMID 36829496, 2023). "In this study, we comprehensively assessed the characteristics of LAG3 in various cancer types using a range of bioinformatics platforms." (PMID 38115039, 2023). "To further investigate the prognostic significance of LAG3, we performed subgroup analyses according to cancer types and the location of LAG3 expression." (PMID 38041068, 2023). "Different molecules targeting other checkpoints such as PD-1, PD-L1 (programmed death-ligand 1) or LAG-3 (lymphocyte-activation gene 3) have rapidly been developed since, revolutionizing the treatment of a wide array of cancer types." (PMID 37108755, 2023). "A number of anti-LAG-3 mAbs have been developed in the past year, and some are currently being evaluated in clinical trials as cancer immunotherapies." (PMID 37670328, 2023). "Like other checkpoint molecules, LAG-3 has been identified in Tregs in the cancer microenvironment, in both natural and inducible activated subsets, where the IL-27/LAG-3 axis enhances the suppressive function." (PMID 37371818, 2023). "Relatlimab (Bristol-Meyers-Squibb), the first anti-LAG-3 mAb, is currently in several clinical trials for cancer therapy." (PMID 37174089, 2023). "We have investigated the expression profile, prognostic significance, and genetic alterations of LAG3 in various cancers while elucidating its characteristic in immune response regulation." (PMID 38115039, 2023). "LAG-3 is an inhibitory receptor that limits the activation and proliferation of the LAG-3-expressing cells and has been identified as an “immune checkpoint” molecule that can be targeted by antibodies to enhance anti-cancer immune responses." (PMID 38187381, 2023). "Several checkpoint proteins, such as CTLA-4, PD-1, TIM-3 and LAG-3, have been identified as regulatory molecules suppressing an effective patient-inherent immune defense of cancer, mainly by T cells." (PMID 37174080, 2023). "A 4-gene inflammatory signature, comprising CD8, PD-L1, LAG-3, and STAT1, was recently shown to be associated with a better overall response to ICB in various cancer types." (PMID 37342338, 2023).